PVT1 (Pvt1 oncogene)
Diseases named in the same sentence as PVT1 in open-access papers (continued):
Sharing a sentence is not in itself a finding about the gene and the disease.
breast cancer (continued). "In breast cancer cell lines, the promoters of PVT1 and MYC compete for the binding of intragenic enhancers that are located within the gene body of PVT1." (PMID 36901971, 2023). "Reduced expression of BLACAT1 in HNSCC; MALAT1, NEAT1 and PVT1 in NPC; FAM201A, PVT1 and LINC00857 in NSCLC; LINC00473, CCAT2and Rpph1 in EC; HOTAIR and LINC00958 in CRC; AFAP1-AS1 and LINC00511 in breast cancer were correlated with radiosensitivity." (PMID 36323697, 2022). "The precise implication of PVT1/PAI-1 and MALAT1, NEAT1/OPN/HOTAIR networks in breast cancer development is still unclear." (PMID 33670447, 2021). "Univariate and multivariate logistic regression analyses were carried out to assess the predictive values of PVT1, MALAT1, NEAT1, HOTAIR, PAI-1, and OPN in breast cancer." (PMID 33670447, 2021). "Thus, PVT1 could act as a useful molecular marker for breast cancer." (PMID 34527584, 2021). "lncRNA PVT1 has been demonstrated for upregulating SOX2 levels (sex-determining region Y box) and critically propagating breast cancer." (PMID 34391433, 2021). "Elevated levels of RSPO1 (an activator of the canonical Wnt signaling pathway with essential roles in ovary determination) combined with PVT1 and MYC transcripts were found in human breast cancer tumors than tumors with low levels of MYC." (PMID 32117705, 2020). "Co‐amplified MYC and PVT1 genes have been identified as candidate oncogenes in ER‐positive, HER2‐positive breast cancers." (PMID 32058674, 2020). "The genes included NDRG1, PVT1, and EXT1, which are co-located in cytoband 8q24, which is frequently amplified in breast cancer." (PMID 32612361, 2020). "Two breast cancers in this series harboured a gain of the 8q24 region, comprising both MYC and the adjacent lncRNA PVT1, which stabilizes the MYC protein and enhances its activity." (PMID 32058674, 2020). "Moreover, PVT1 expression in plasma has a positive correlation with histological grade, expression of Ki-67, tumor size and lymph node metastasis, and might act as an independent prognostic factor for the survival of breast cancer patients." (PMID 31497532, 2019). "Its localization is both cytoplasmic and nuclear in SiHa (cervical cancer cell line) while in 85% of SK-BR-3 breast cancer cells, a nuclear co-localization of MYC and PVT1 was observed." (PMID 30809433, 2019). "PVT1 promotes cell progression, growth, invasion, and acquisition of stem cell-like properties by stabilizing FOXM1 and NOP2 proteins in breast cancer and hepatocellular carcinoma, respectively." (PMID 30809433, 2019). "The locus, including the gene desert and its flanking genes, MYC, PVT1 and FAM84B, is also frequently amplified in human breast cancer." (PMID 30526553, 2018). "Compared with breast adjacent tissues, AFAP1-AS1, PVT1, HYMAI were downregulated in most breast cancer tissues, and lncRNA PVT1, BANCR, HCG18 were upregulated in lung cancer." (PMID 28938549, 2017). "AHIF, MALAT1, SNHG6, UCA1 expression levels increased in breast cancer tissues compared with their counterpart adjacent tissues, while AFAP1-AS1, PVT1, HYMAI had lower expression in tumors." (PMID 28938549, 2017). "In breast cancer models, HOTAIR has been shown to promote metastasis through re-location of PRC2, and PVT1 expression correlates with MYC protein levels and influences its stability." (PMID 28875933, 2017). "LncRNA PVT1 was lower in grade I and III breast cancers, and SNHG6 was upregulated in grade I breast cancer." (PMID 28938549, 2017). "Approximately 10% of all human breast cancers show co-amplification of MYC and PVT1, with a particularly high proportion (62%) among HER2+ tumors." (PMID 28430642, 2017). "In a breast cancer mouse model, Tseng and coworkers observed a halving in the proliferation upon either MYC or PVT1 knockdown." (PMID 25883951, 2015).
breast cancer (continued). "At the heart of this phenomenon is the lncRNA PVT1, as illustrated by both the width of its antagonist mRNAs in normal-MMI-network, and the relevance of the latter in breast cancer." (PMID 25033876, 2014). "Furthermore, the PVT1 promoter, located only 55 kb away from the MYC promoter, functions as an onco-suppressor in breast cancer independently of the oncogenic PVT1 lncRNA." (PMID 37443779, 2023). "In addition, PVT1 binds to the UPF1 protein, thereby inducing epithelial–mesenchymal transition, proliferation and metastasis in breast cancer cells." (PMID 34922601, 2021). "For instance, PVT1 upregulates the expression of miR-1207-5p to repress the expression of signal transducer and activator of transcription 6 (STAT6) and cyclin inhibitors, thus enhancing cell proliferation and colony formation in breast cancer." (PMID 34527584, 2021). "Differential expression of PVT1 alternatively spliced transcripts in breast cancer have not been previously investigated." (PMID 33801373, 2021). "PVT1 has been shown to directly bind and stabilize the KLF5 proteins in breast cancer." (PMID 31320749, 2020). "For example, PVT1 acts as a competitive endogenous RNA that forms a tight network with protein-coding mRNAs, such as CDH1, TP73, TP31, RUNX1, and RUNX via microRNA-200, thereby regulating breast cancer progression." (PMID 32992461, 2020). "Increased levels of PVT1 also significantly induced the expression of miR-1207-5p in breast cancer samples compared to non-cancerous controls." (PMID 31590453, 2019). "The “promoter-enhancer competition” between PVT1 and MYC is currently only found in breast cancer cell lines and, thus, requires further exploration regarding whether this competition commonly exists in other MYC-driven cancers." (PMID 31309249, 2019). "Pvt1 transcript levels showed a non-significant reduction in the mammary gland and mammary tumor samples." (PMID 30526553, 2018). "Association of MYC, PVT1, or FAM84B transcript levels with any of the breast cancer risk alleles has not been reported." (PMID 30526553, 2018). "The findings revealed that PVT1, SNHG6, NEAT1 may serve as a prognostic marker for breast cancer combined with primary lung cancer." (PMID 28938549, 2017). "PVT1 is reported to stabilize and upregulate MYC protein in breast cancer cells." (PMID 28265576, 2017). "In this regard, Gray and colleagues were able to induce apoptosis in ovarian or breast cancer cell lines by silencing of PVT1 in cell lines with amplified chr.8q24 but they found no apoptosis in non-amplified cell lines." (PMID 26703666, 2015). "By analysing the breast cancer data set provided by TCGA, we found that PVT1 acts as ceRNA in the normal-MMI-network but not in cancer." (PMID 25883951, 2015). "The results showed that five lncRNAs including HOTAIR, DANCR, PVT1, LINC00511, and NEAT1 and 16 miRNAs and five of their targets—VEGFA, BTG2, E2F3, IRAK1, and SMAD4—have significantly different expression patterns in normal individuals compared to those with breast cancer." (PMID 36726376, 2023). "PVT1 has been identified as a prognostic biomarker and played a critical role in the development of pancreatic ductal adenocarcinoma via triggering cytoprotective autophagy, and it affected EMT and cell proliferation and migration via modulating CDKN1A expression in breast cancer." (PMID 33868366, 2021). "However, to our knowledge, the significance of PVT1 exon 9 in breast cancer was not previously investigated." (PMID 33801373, 2021).
breast cancer (continued). "In addition, a group of researchers detected the serum levels of lncRNAs PVT1, HOTAIR, NEAT1, and MALAT1 from Egyptian breast cancer and fibroadenoma patients, as well as healthy donors, and found that serum PVT1, HOTAIR, and NEAT1 could serve as potential biomarkers for breast cancer." (PMID 38505593, 2024). "In breast cancer models PVT1 RNA levels correlate with MYC protein, yet PVT1 and c-MYC are not always co-amplified." (PMID 28747406, 2017).
pancreatic cancer (93 papers, 2015 to 2025). "These cells expressed plasmacytoma variant translocation 1 (PVT1) to promote the activation of kynurenine pathway in pancreatic cancer, contributing to tumor immune exclusion." (PMID 40248695, 2025). "Detection of PVT1 in saliva is a diagnostic biomarker with 96.4% sensitivity and 63.6% specificity in pancreatic cancer." (PMID 38559560, 2024). "Plasmacytoma Variant Translocation 1 (PVT1) has been positively associated with stage and negatively associated with prognosis in pancreatic cancer." (PMID 37444595, 2023). "For instance, the lncRNA plasmacytoma variant translocation 1 (PVT1) activates the Wnt/β-catenin pathway to promote gemcitabine resistance of pancreatic cancer." (PMID 34893064, 2021). "This is the case of lncRNA plasmacytoma variant translocation 1 (PVT1) that, highly expressed in several cancers including pancreatic cancer, promotes exosome secretion." (PMID 34943863, 2021). "Increased expression of the lncRNA PVT1 in cancer tissue is associated with poor prognosis in pancreatic cancer patients." (PMID 32201527, 2020). "In this study, we discovered that the lncRNA PVT1 is up-regulated in gemcitabine resistant human pancreatic cancer cells, and subsequent gain- and loss-of-function experiments revealed that PVT1 promotes gemcitabine resistance in vitro and in vivo." (PMID 32727463, 2020). "For example, lncRNA PVT1 accelerated tumorigenesis of non-small cell lung cancer and was associated with a poor prognosis in patients with pancreatic cancer." (PMID 27813492, 2016). "Five well-documented lncRNAs: H19, HOTAIR, HOTTIP, MALAT1, PVT1, which are most closely associated with pancreatic cancer from previous studies were selected as putative lncRNA biomarkers." (PMID 27028998, 2016). "The minor allele of the SNP that marks the signal on 8q24.21 (rs10094872) and was associated with increased risk of pancreatic cancer, was associated with decreased PVT1 expression (β = −0.23, P = 0.0053)." (PMID 27579533, 2016). "In our results, significantly lower infiltration levels of CD8+ T cells were observed in the high-risk group, suggesting that PVT1-MYC duet could induce an immunosuppressive microenvironment of pancreatic cancer." (PMID 39376555, 2024). "As PVT1 promotes human pancreatic cancer gemcitabine resistance, which is also associated with cellular autophagic activity, we then investigated whether the PVT1/miR-619-5p axis could target autophagy-related gene(s)." (PMID 32727463, 2020). "In addition, studies have found that gemcitabine can inhibit the growth of pancreatic cancer cells by decreasing PVT1 levels and increasing PVT1 encoded miRNAs, such as the miR-1207 pair (miR-1207-5p/3p)." (PMID 31309249, 2019). "In pancreatic cancer, PVT1 expression is associated with gemcitabine sensitivity in human pancreatic cancer cells and may be associated with poor prognosis." (PMID 27579533, 2016). "Taken together, these results demonstrated that PVT1 induced gemcitabine resistance is associated with increased Wnt/β-catenin signaling and autophagic activity, and inhibition of Wnt/β-catenin signaling or autophagy increased the sensitivity of human pancreatic cancer cells to gemcitabine." (PMID 32727463, 2020). "Recent studies have reported that HIF-1α responsible for lncRNA PVT1-mediated pancreatic cancer enhancing." (PMID 38740637, 2024). "It has been documented that the existence of a positive feedback loop between the long non-coding RNA (lncRNA) PVT1 and the Wnt/β-catenin signaling pathway, which played a role in the development of gemcitabine resistance in human pancreatic cancer." (PMID 39501138, 2024). "On the other hand, studies have shown that PVT1 is involved in the induction of gemcitabine resistance by binding to the EZH2 and forming the PVT1/EZH2 complex in pancreatic cancer." (PMID 38559560, 2024).
pancreatic cancer (continued). "Similar rescue experiments demonstrated that PVT1 can also promote the proliferation and migration of pancreatic cancer cells through CDC6, further confirming that CDC6 is a crucial downstream element in the PVT1-MYC duet’s facilitation of pancreatic cancer." (PMID 39376555, 2024). "Currently circ-PVT1 is mostly used to study pancreatic cancer, renal cell carcinoma and colorectal cancer." (PMID 38733530, 2024). "In conclusion, our study constructed a prognostic model for pancreatic cancer based on three PVT1-MYC duet-related genes to stratify patients and predict prognosis." (PMID 39376555, 2024). "We subsequently validated through rescue experiments that PVT1 can promote the proliferation and migration of pancreatic cancer cells via MYC." (PMID 39376555, 2024). "Due to the regulatory role of HAT1 in the PVT1 expression, HAT1 can be considered one of the therapeutic targets for reducing the oncogenic effects of PVT1 on pancreatic cancer cells." (PMID 38559560, 2024). "lncRNA PVT1 was found to enhance gemcitabine resistance of pancreatic cancer not only by accelerating assembly of the autophagy-specific complex I (PtdIns3K-C1) to activate autophagy but also by activating the pygo-mediated Wnt/β-catenin pathway." (PMID 36829596, 2023). "CDKN1A/p21 downregulation is suggested to be necessary for Plasmacytoma Variant Translocation 1 (PVT1) lncRNA-induced EMT in triple-negative breast cancer cells and in pancreatic cancer cells." (PMID 38139316, 2023). "Integrated data mining analysis identified the PVT1/miR-20b/CCND1 axis as a promising pathway-related ceRNA axis in the progression of pancreatic cancer." (PMID 37628628, 2023). "PVT1 has been shown to promote GEM resistance in pancreatic tumor cells by increasing WNT and autophagic activities." (PMID 37580768, 2023). "For instance, lncRNA PVT1 promotes gemcitabine resistance of pancreatic cancer via activating the Wnt/β-catenin and autophagy pathway." (PMID 35607322, 2022). "LncRNA PVT1 activates Wnt/-catenin and autophagy to enhance gemcitabine resistance in pancreatic cancer." (PMID 36313374, 2022). "For example, PVT1 were found to be upregulated in pancreatic cancer and overcome gemcitabine resistance through sponging miR-619- 5p, leading to upregulation of Pygo2, which is a downstream target of miR-619-5p." (PMID 36266267, 2022). "For instance, HIF1α directly bond to the promoter of KDM4A-AS1 and upregulated it expression in hepatocellular carcinoma 36, and HIF1α upregulated PVT1 transcription by binding to its promoter region in pancreatic cancer." (PMID 35414787, 2022). "It was also shown that PVT1 promoted pancreatic cancer and glioma progression via the autophagy signaling pathway." (PMID 35256612, 2022). "In this way, curcumin suppresses the expression of EZH2 as a subunit of PRC2 and its related lncRNA PVT1 to prevent pancreatic cancer progression and increase gemcitabine sensitivity." (PMID 35236381, 2022). "Meanwhile, numerous studies have revealed the involvement of lncRNA in gemcitabine resistance in pancreatic cancer, including PVT1, HIF1A-AS1, UCA1, etc.." (PMID 36371178, 2022). "It has been reported that curcumin administration can promote sensitivity of pancreatic cancer cells to gemcitabine via regulating the expression level of PVT1 and its interaction with EZH2." (PMID 35236381, 2022). "Overexpression of PVT1 in pancreatic cancer cell lines can enhance sensitivity to Gemcitabine by regulating autophagy, thus inhibiting the growth of pancreatic cancer." (PMID 35813295, 2022). "This study suggests that HAT1 regulates the sensitivity of pancreatic cancer to gemcitabine by regulating PVT1/EZH2 complex, highlighting the importance of HAT1 in the development of gemcitabine resistance in pancreatic cancer." (PMID 34564701, 2021). "Pancreatic cancer patients with high expression of PVT1 had shorter overall survival times compared to those with low expression of PVT1." (PMID 34439315, 2021).